TNF (tumor necrosis factor)
Diseases named in the same sentence as TNF in open-access papers (continued):
Sharing a sentence is not in itself a finding about the gene and the disease.
cancer (continued). "In oncology, daily oral administration of ginseng or ginsenoside Rb1 in mice bearing colon C26 cancer cells results in reduced levels of TNF-α and IL-6 cytokines in serum, without modifications of tumor growth." (PMID 36139563, 2022). "SSD inhibited TNF-α-induced NF-κB activation and the expression of its target genes, which are involved in cancer cell proliferation, invasion, angiogenesis, and survival, greatly potentiating TNF-α-mediated cell death in HeLa and HepG2 cancer cells." (PMID 36547471, 2022). "In cancer-bearing mice, cancer tissues modulate the microenvironment in the distal organ by releasing various cytokines, including vascular endothelial growth factor A (VEGFA), TNF, transforming growth factor-β (TGFβ), and G-CSF, to prepare for subsequent cancer metastasis." (PMID 34674757, 2021). "Moreover, studies have shown that the release of TNF-α and TGF-β1 from macrophages can synergistically increase the migration rate and persistence of 3D cancer cells." (PMID 35069596, 2021). "Secretion of proinflammatory adipokines such as tumour necrosis factor-α (TNF-α) and interleukin-6 (IL-6) by dysfunctional adipose tissue and an increase in inflammatory factors, such as C-reactive protein (CRP), are likely to promote cancer development." (PMID 33492550, 2021). "In addition, the significantly higher production of TNF-α and IFN-γ were found in CD8+ fraction of the anti-MUC1-CAR4 T cells after co-culture with MUC1-expressing cancer cells." (PMID 33737613, 2021). "Based on expression of high levels of TNF-α, IFN-γ, and granzyme B, CD8+ TRM cell infiltration in various human cancers is correlated with favorable clinical outcomes, and CD8+ TRM cells have emerged as a predictive marker of survival in several human epithelial cancers." (PMID 34604029, 2021). "The absence of GPx1 augmented TNF-α-induced apoptosis in various RIPK3-negative cancer cells by markedly elevating the level of cytosolic H2O2, which is derived from mitochondria." (PMID 34158609, 2021). "Lower concentrations of allicin did not affect the gene expression of TNF-alpha and endothelin but all three concentrations of allicin were found to be affecting the gene expression of IL-8 significantly in both cancer cells and sorted cancer stem cells." (PMID 34071008, 2021). "Furthermore, in renal cell carcinoma, the cytokines TNF and MMP-9 were found to be useful as a predictive biomarker for the activity of the anti-cancer drug sunitinib activity." (PMID 34307156, 2021). "TNF-α as well play a negative role in modulating lipid biosynthesis and storage in cancer cachexia via downregulation PPARγ pathway." (PMID 34888248, 2021). "KDM6B is upregulated via nuclear factor-κB (NF-κB) binding to its promotor region by tumor necrosis factor α (TNFα), and that KDM6B in turn upregulates mitogen-activated protein kinase (MAPK) pathway, thereby promoting cancer cell growth and survival in a catalytically-independent manner." (PMID 34950587, 2021).
cancer (continued). "We found that a majority of these steps were activated significantly higher in the TNF cluster 1 than cluster 2, including T-cell recruiting, CD8 T-cell recruiting, NK cell recruiting, infiltration of immune cells into tumors, and killing of cancer cells." (PMID 35174161, 2021). "In addition, TNF-α upregulates transforming growth factor-alpha (TGF-α), an oncogene that can increase cell proliferation and promote cancer." (PMID 34940031, 2021). "We first stimulated primary cancer cells of KPC and KPNeC pancreata with TNF-α." (PMID 34572768, 2021). "Comparative analysis of pain mediators TNF-alpha, IL-8, and endothelin at both RNA and protein levels for normal epithelial cells, cancer cells, and cancer stem cells was carried out with and without allicin treatment." (PMID 34071008, 2021). "In the second group, thirty-five significantly enriched KEGG pathways were obtained, among which ubiquitin-mediated proteolysis, the TNF signaling pathway, the TGF-β signaling pathway, proteoglycans in cancer, the Hippo signaling pathway, RNA transport, and adherence junctions were included." (PMID 34884950, 2021). "Firstly, although TNFα can stabilize PD-L1 protein by inhibiting the breakdown via ubiquitination in cancer cells, we did not tackle the effect of cytokines on the stability and membrane translocation of PD-L1." (PMID 34445462, 2021). "To date, there are no studies exploring the safety and effectiveness of non-anti TNF-alpha biological drugs for patients with current cancer." (PMID 33540674, 2021). "Along those lines, it has been shown that MAPK–inhibitors used for the treatment of BRAF-mutant melanomas induce TNF-α production by a macrophage population that triggers the expression of MITF (microphthalmia transcription factor), resulting in the resistance of cancer cells to MAPK inhibitors." (PMID 33803675, 2021). "Moreover, we demonstrated that FC2 can induce cancer cell death as a single agent and, more potently, in combination with the Smac-mimetic SM83 or with the cytokine TNF." (PMID 34938412, 2021). "Since adipocytes from obese individuals express higher levels of inflammatory cytokines, such as IL6 and TNFα, it is possible that obese adipocytes are already more “CAA-like” and more supportive of cancer cells, even before complete trans-differentiation into a distinct CAA phenotype." (PMID 33968771, 2021). "Tumor necrosis factor (TNF)-related apoptosis-inducing ligand (TRAIL) belongs to the TNF family that can stimulate apoptosis in various cancer cells including NPC cells without affecting the human healthy cells." (PMID 33858433, 2021). "The TNFα is known to induce inflammation and cancer; however, whether TNFα-induced MAP4K4 promotes cancer directly or indirectly is unclear." (PMID 34511598, 2021). "Chromenes are also an important class of heterocyclic compounds which exhibit attractive pharmacological properties, such as antitumor, anti-vascular, antioxidant, antimicrobial, sex pheromone, tumor necrosis factor-α (TNF-α) inhibitor, cancer therapy and central neuroprotective activities." (PMID 34822481, 2021). "The KEGG results showed that FSG may be involved in the cancer signaling pathway, the PI3K-Akt signaling pathway, the HIF1 signaling pathway, and the TNF signaling pathway." (PMID 33747100, 2021). "The candidate common targets were principally enriched in pathways in cancer (hsa05200 and hsa05205), the HIF-1 signaling pathway (hsa04066), the TNF signaling pathway (hsa04668), the PI3K-Akt signaling pathway (hsa04151) and leukocyte transendothelial migration (hsa04670)." (PMID 34209942, 2021).
cancer (continued). "The binding activates the CD4+ and CD8+ T cells which in turn will produce pro-inflammatory cytokines [respectively tumor necrosis factor (TNF)-α, anti-tumor cytokine interferon-gamma (IFN-γ), Granzyme B, and perforins], leading to the destruction of cancer cells." (PMID 36046144, 2021). "Moreover, M.tb can induce the release of inflammatory mediators, e.g., tumor necrosis factor (TNF)-α and interleukin (IL)-1, IL-2, and IL-12, which can be viewed as cancer promotors." (PMID 34361097, 2021). "KEGG pathway analysis indicated that the 49 key signaling pathways may be the antiglioma mechanisms of luteolin that include pathways in cancer, PI3K-Akt-, TNF-, and MAPK-signaling pathways." (PMID 34873410, 2021). "The antitumor effect of γδ T cells is achieved by their virtue to produce proinflammatory cytokines interferon-γ (IFN-γ) and tumor necrosis factor-α (TNF-α), which act in cohort with other factors to induce antitumor immunity and inhibition of cancer angiogenesis." (PMID 34526984, 2021). "And WMP might have effects on the outcomes of UC through the IL-17 pathway, TNF pathway, AGE-RAGE pathway, and cancer-related pathways." (PMID 34970312, 2021). "We conclude from our current data that AWP1 has negative effects on cancer-promotion through its regulation of NF-κB-dependent activation induced by TNF-α." (PMID 33816268, 2021). "TNF-α and TGFβ1 upregulate cyclooxygenase-1 (COX-1) and COX-2 expressions of mast cells and PG generation, which substantially affects skin carcinogenesis development by enhancing epidermal proliferation and stimulating inflammation within a cancer." (PMID 33917793, 2021). "IL-6 cooperates with TNF-α also in stimulating the Janus kinase (JAK)-signal transducer and activator of transcription (STAT), the JAK2/STAT3 pathway, which is involved in inflammation, cancer progression, muscle mass wasting, and cancer-related cachexia." (PMID 34684523, 2021). "In addition, several studies in different types of cancers have shown the potential of ICD inducers to increase the levels of pro-inflammatory cytokines, including TNF-α, to produce an immunogenic TME." (PMID 33919653, 2021). "This may be through EZH2, which is positively influenced by TNFα/IL-1β signaling and has been shown to hypermethylate the ODZ4 promoter in cancer, resulting in repressed miR-708 expression." (PMID 33776573, 2021). "In the current study, CN extracts were not affecting the proliferation and migration of cancer cells but suppressed the pro-inflammatory cytokines such as IL-6, IL-1β, and TNF-α." (PMID 34379689, 2021). "Interestingly, the same transcription factors are also emerging as key regulators for the expression of mediators such as cytokines (TNF-α), chemokines (CCL2, CXCL6, GRO, CXCL8, CXCL11), and growth factors (GM-CSF) in cancer cells." (PMID 34567000, 2021). "This includes inflammatory signals (e.g., IL-1, IL-6, and tumor necrosis factor (TNF)), TGF-β, physical changes in the ECM, contact signals with cancer cells, and DNA damage, resulting in a gain of proliferation, secretory phenotype, migration, and ECM production and remodeling." (PMID 33673405, 2021). "CAR-T cells mediate antitumor effects by specifically recognizing the target molecules on cancer cells and subsequently destroying the cells through cytotoxic granules such as perforin and granzymes, along with inflammatory cytokines such as IFN-γ and TNF-α." (PMID 33673398, 2021). "The top ten pathways were regulation of actin cytoskeleton, TNF signaling pathway, MAPK signaling pathway, axon guidance, ECM–receptor interaction, proteoglycans in cancer, focal adhesion and PI3K-Akt signaling pathway, cell adhesion molecules and pathway in cancer." (PMID 33470407, 2021).
cancer (continued). "Despite much evidence correlating TNF with cancer severity and prognosis, clinical trial outcomes are not conclusive." (PMID 33917839, 2021). "TNF-α exerts its effects by binding to TNF-α receptors, TNFR1 and TNFR2, which can activate signaling pathways including c-Jun N-terminal kinase (JNK), nuclear factor-kappa B (NF-κB) and a caspase cascade in human cancer cells." (PMID 33961948, 2021). "First, we excluded patients with malignancy or undergoing TNF-α antagonist therapy, whose TNF-α secretion may be disturbed." (PMID 34225667, 2021). "Although the TNF-α-initiated cachexic changes in C2C12 cells comprise a classic cell model of cancer cachexia, we consider that TNF-alpha is certainly not the only cytokine that is important for cancer cachexia." (PMID 34724970, 2021). "During the “elimination” phase, the natural killer (NK) cells, CD4+Th1, CD8+CTL (cytotoxic T lymphocyte), and cytokines including tumor necrosis factor-α (TNF-α), interferon-α, interferon-β, interferon-γ and interleukin-12(IL-12) are the primary factors to recognize and eliminate cancer cells." (PMID 35127500, 2021). "Moreover, the upregulation of TGF-β, TNF-α and COX-2 promote EMT in different cancers that results into the poor prognosis of cancer therapy." (PMID 34588926, 2021). "It was found that, under the situation of irradiation, the concentration of TNF-α in the medium had a much higher level but IL-10 became much lower than those of nonirradiated cancer cells." (PMID 33867819, 2021). "In cancer patients, besides IL-17, Th17 cells produce high levels of other immunological mediators, such as GM-CSF, IL-2, TNF and IFN-γ, but not IL-10." (PMID 34646761, 2021). "The work showed that TNF can simultaneously promote cancer cell migration while also limiting the migration-promoting abilities of myofibroblasts, but did not study the role of anti-TNF antibodies in the context of cancer immunotherapy." (PMID 34085677, 2021). "While on the other hand, the treatment group of the cancer tissue with PFT-HSA-TFT-Cy7 and PFT-Hcy-HSA-Cy7 shows a significant decrease in level of TNF-α mRNA, with an average decrease in fold change as 1.9-fold and 2.3-fold at 1 μM and 1.5-fold and 1.9-fold at 3 μM with respect to their controls." (PMID 33928164, 2021). "In nonmetastatic cancer patients, T cells were negatively correlated with IL-6 and IL-10 and were positively correlated with IL-4 and TNF-α." (PMID 34712741, 2021). "Cancer cells produce and secrete inflammatory cytokines such as interleukin 1 (IL1), tumour necrosis factor alpha (TNF-α) and vascular endothelial growth factor (VEGF), which mediate interactions between cancer cells and host cells, including endothelial cells, platelets, monocytes and neutrophils." (PMID 34205695, 2021). "Hence, when the TNFα-secreting TAMs were depleted upon clodronate treatment of LLC-engrafted mice, PD-L1 expression significantly increased in the aerobic cancer cells." (PMID 34445397, 2021). "The results revealed that angiogenesis, glycolysis, and EMT were the biological process most correlated with CD44 expression, while the TNFα signaling via NFκB, angiogenesis, IL6_JAK_STAT3 pathway, and EMT were correlated with TNFRSF12A in cancer cells across CRC, LC, and SCC." (PMID 34676217, 2021). "Furthermore, cytokines (IL-6 or tumor necrosis factor-alpha (TNF-α) trigger the NF-κB and STAT3 pathways, which are essential for enhancing FSCN1 expression in cancer." (PMID 34830909, 2021).
cancer (continued). "In response to anti-cancer drugs, patients with low CSS exhibited higher sensitivities to molecular drugs, such as Roscovitine (CDKs inhibitor), Lenaidornide (TNF-α inhibitor), MK2206 (Akt 1/2/3 inhibitor), and especially increased response to anti-PD-1/L1 immunotherapy." (PMID 34872577, 2021). "We can conclude, that TNFα overexpression in our cancer cells was not able to hit CSCs subpopulation in vitro and is not responsible for the loss of tumorigenic potential of engineered cells in vivo." (PMID 33957885, 2021). "Among the top-ranked PRC2+-CGI-enriched pathways, some were shared across multiple cancer types, including “Epithelial mesenchymal transition (EMT)”, “KRAS signaling up”, and “TNFα signaling via NF-KB” pathways, while others such as “Estrogen response early” were specific to a single cancer type." (PMID 33931649, 2021). "While our results grossly recapitulate the neutrophilia noted with human cancers, there was a decrease in circulating neutrophils at the four-week time-point between the isotype and anti-TNFα treated groups, albeit not statistically significant." (PMID 34650923, 2021). "In an attempt to predict the most common interactions between the different TNFα-signaling members within the lung TME, we compared the overall TNF, TACE, TNFR1, and TNFR2 expression profiles within a healthy tissue and TCGA pan-cancer LUAD transcriptomic data set." (PMID 34445397, 2021). "MSCs migrate to the site of cancer development characterized by a pro-inflammatory microenvironment, the secretion of pro-inflammatory cytokines like IFN-γ and TNF-α enhances in MSCs the expression of cytokines, enzymes, and growth factors that through immunosuppression promote cancer progression." (PMID 34680425, 2021). "Furthermore, the novel extract sufficiently adjusted the production of proinflammatory cytokines including TNF-α, TGF-β, IL-6, and IL-8, which play a crucial role in inflammatory events and cancer development." (PMID 34513674, 2021). "Tumor necrosis factor (TNF) is a major inflammatory cytokine having both positive and negative effects on cancer." (PMID 34888239, 2021). "TRAIL is a cytokine from the tumor necrosis factor (TNF) superfamily that selectively induces apoptosis in cancer cells without displaying toxicity towards healthy cells." (PMID 34684883, 2021). "Furthermore, certain vital KEGG pathways, such as proteoglycans in cancer, adrenergic signaling in cardiomyocytes, the AMPK signaling pathway, the HIF-1 signaling pathway and the TNF signaling pathway, were also enriched." (PMID 33428603, 2021). "Tumor necrosis factor (TNF)-associated apoptosis-inducing ligand (TRAIL) is considered as a promising anticancer molecule, as it can selectively induce apoptosis in cancer cells without damaging normal cells." (PMID 32695666, 2020). "Prx-1 exerts DNA-damage-associated functions, increasing the production of proinflammatory mediators, including nitric oxide (NO) metabolites, tumor necrosis factor-α (TNF-α), and interleukin-6 (IL-6), and is also induced by radiation in various types of cancer cells in vitro." (PMID 33316778, 2020). "Next, we investigated whether IL-17 and TNF-α affected ROS levels in RA and OA FLS, because ROS have been shown to directly induce cell migration and invasion in the context of cancer." (PMID 32414400, 2020). "Overexpression of TNF-α is common in ovarian cancer, and in the presence of SMAC mimetic therapy, may drive cancer cells towards apoptosis." (PMID 33334024, 2020). "Tumor necrosis factor (TNF)-related apoptosis-inducing ligand (TRAIL) and Mu-2/AP1M2 domain containing, death-inducing (MUDENG, MuD) have been established for their ability to bring about cell death specifically in cancer cells." (PMID 32759789, 2020).